GPBP1 (GC-rich promoter binding protein 1)
Description:
Functions as a GC-rich promoter-specific transactivating transcription factor.
Synonyms: GPBP; SSH6; DKFZp761C169; VASCULIN
Tractability: Antibody: its Gene Ontology location is reachable by antibodies, with high confidence; the Human Protein Atlas places it where antibodies can reach. PROTAC: ubiquitination databases record sites on it.
Gene: Protein-coding gene on chromosome 5 (57,173,821 to 57,265,668, forward strand). Ensembl gene ENSG00000062194.
Subcellular location: Nucleus; Cytoplasm
Subcellular location (Human Protein Atlas): Cytosol; Vesicles; Plasma membrane
Gene Ontology:
Molecular function: protein binding; DNA-binding transcription factor activity; DNA binding; RNA binding
Biological process: regulation of DNA-templated transcription; DNA-templated transcription; positive regulation of DNA-templated transcription
Cellular component: cytoplasm; cytosol; nucleus
Genetic constraint (gnomAD): Loss-of-function variants: 4 observed, 33.25 expected, observed/expected ratio (o/e) 0.12, 90% interval 0.058 to 0.28. The upper end of that interval is the gene's LOEUF score, 0.28, which puts it in group 1 of 6, group 1 being the genes least tolerant of losing a copy. Missense variants: 370 observed, 435.46 expected, observed/expected ratio (o/e) 0.85, 90% interval 0.78 to 0.93. Synonymous variants: 147 observed, 145.11 expected, observed/expected ratio (o/e) 1.01, 90% interval 0.88 to 1.16.
Homologues: Orthologues: chimpanzee GPBP1 (99% identical), macaque GPBP1 (99% identical), pig GPBP1 (97% identical), dog GPBP1 (97% identical), rat Gpbp1 (96% identical), mouse Gpbp1 (95% identical), rabbit GPBP1 (95% identical), guinea pig GPBP1 (87% identical), tropical clawed frog gpbp1 (42% identical). Paralogues in human: GPBP1L1 (43% identical).
Diseases named in the same sentence as GPBP1 in open-access papers:
GPBP1 is named in the same sentence as 10 diseases in open-access papers, as found by Europe PMC text mining. Sharing a sentence is not in itself a finding about the gene and the disease. The quoted sentences say what the papers report.
breast cancer (3 papers, 2018 to 2022). A primary or metastatic malignant neoplasm involving the breast. "There was a strong concordance between genes upregulated upon GPBP1 knockdown and genes whose expression level was higher in breast cancers with GPBP1 loss." (PMID 29669295, 2018). "On the other hand, rat chromosome 2q14 (which harbors Gpbp1, Map3k1 and Il6st) coincides with Mamtr3 (also known as Mcs1b or Mcs10), another mammary-cancer susceptibility QTL for which the COP allele confers resistance to chemically induced mammary carcinogenesis." (PMID 34388197, 2021). "GPBP1 lies on chromosome 5q11, a region focally deleted in approximately 5% of TCGA HGSOCs and 4% of TCGA breast cancers." (PMID 29669295, 2018).
Hypercholesterolemia (2 papers, 2021 to 2024). An increased concentration of cholesterol in the blood. "GPBP1 is believed to be involved in cholesterol metabolism and was observed to be downregulated in the vascular tissue of animal models exposed to hypercholesterolemia." (PMID 39766777, 2024).
Hypertension (2 papers, 2021 to 2022). The presence of chronic increased pressure in the systemic arterial system. "GPBP1, also known as Vasculin, is a promoter binding protein that is reported to have roles in atherosclerosis, hypertension, hypercholesterolemia, and Alzheimer’s disease." (PMID 35893234, 2022).
ovarian carcinoma (2 papers, 2018 to 2022). A malignant neoplasm originating from the surface ovarian epithelium. "Further analysis of samples with GPBP1 loss in TCGA ovarian cancer samples also reflected the increased expression of a number of the same HR factors, indicating a similar function of GPBP1 in these two disease types." (PMID 29669295, 2018). "We identify that ARID1A loss confers resistance to PARP inhibitors in cells and ovarian cancer patients and that loss of GPBP1 causes resistance to cisplatin and PARP inhibitors through the regulation of genes involved in homologous recombination." (PMID 29669295, 2018). "We next asked whether this enhancement in HR gene expression upon GPBP1 loss resulted in drug resistance in ovarian cancer patients treated with platinum-containing therapy." (PMID 29669295, 2018). "Therefore, GPBP1 loss contributes to platinum resistance in ovarian cancer through the increased expression of genes involved in HR." (PMID 29669295, 2018).
viral infection (1 paper, 2021). "Notably, we detect DIUs for several of the same genes (Setd5, Arhgap12, Gpbp1, and Eri2), suggesting that hnRNP K’s role in viral infection is conserved between mice and humans and may, in part, be mediated by the same alternative splicing events." (PMID 34305890, 2021).
cancer (2 papers, 2018 to 2022). A tumor composed of atypical neoplastic, often pleomorphic cells that invade other tissues. "This hypothesis was particularly intriguing, since GPBP1 knockdown caused resistance to BMN673 in BRCA1 mutant cancer cell lines, suggesting that GPBP1 loss may bypass the requirement of BRCA1 for HR." (PMID 29669295, 2018). "Drawing from our RNA-seq analysis, we next asked whether the expression of HR factors was also elevated in human cancer samples harboring GPBP1 loss and whether it might contribute to drug resistance." (PMID 29669295, 2018). "Genes containing AS events associated with overall survival are known components of cancer-related pathways, including regulation of transcription (E2F4, ZNF730, GPBP1, POLR2J, SP2, and CIART), cell cycle (E2F4 and GTSE1), or cell-cell adhesion (CEACAM1, MMP14, EPS8L2, AP3D1, AFDN, and PAK4)." (PMID 35044822, 2022).
GPBP1 also shares sentences with these, for which no sentence is quoted: Alzheimer disease (1 paper); atherosclerosis (1); breast tumors (1); glomerulosclerosis (1).